TIMP2 (TIMP metallopeptidase inhibitor 2)
Diseases named in the same sentence as TIMP2 in open-access papers (continued):
Sharing a sentence is not in itself a finding about the gene and the disease.
resistant hypertension (1 paper, 2019). "One such gene is TIMP2, coding for tissue inhibitor of metalloproteinases 2, which is part of a peptidase family involved in the degradation of the ECM, linked with resistant hypertension and arterial stiffness." (PMID 30931314, 2019).
retinoblastoma (1 paper, 2020). A malignant tumor that originates in the nuclear layer of the retina. "Expression of MMP-2 and TIMP-2 was also studied in retinoblastoma (RB), the most common primary malignant intraocular cancer in children." (PMID 32751899, 2020).
scleroderma (1 paper, 2020). Scleroderma is a rare autoimmune connective tissue disorder characterized by abnormal hardening of the skin and, sometimes, other organs. "The results obtained in the present study showed that the mean concentration of both TIMP-1 and TIMP-2 in the blood plasma of patients with scleroderma was higher, compared to the concentrations of these inhibitors in the blood plasma of healthy individuals." (PMID 32382564, 2020).
spinal stenosis (1 paper, 2022). Narrowing of the spinal canal. "This hypothesis was confirmed by the significant association between elevated TIMP-1 and TIMP-2 expression in LF fibroblasts and spinal stenosis, a reproducible finding of several different experiments of various methods." (PMID 36269774, 2022).
Strabismus (1 paper, 2017). A misalignment of the eyes so that the visual axes deviate from bifoveal fixation. "Some of the trends in gene expression differences between horizontal muscles from patients with strabismus, notably for MMP2 and TIMP2, were similar to those reported previously." (PMID 29302405, 2017).
synovial sarcoma (1 paper, 2013). "Malignant synovial sarcoma cells did not secrete u-PA; however, MMP-2 and -9 secretions by SW-982 were inhibited by NM and secretion of TIMP-2 was enhanced by NM." (PMID 23661254, 2013).
systemic lupus erythematosus (1 paper, 2021). An autoimmune multi-organ disease typically associated with vasculopathy and autoantibody production. "MMP-2, TIMP-2, and MMP-2/TIMP-2 ratios may act as biomarkers for susceptibility to systemic lupus erythematosus (SLE)." (PMID 33777140, 2021).
testicular degeneration (1 paper, 2023). "Although other studies have identified TIMP-2 in the SP of bulls with high fertility and in human spermatozoa with a low degree of DNA fragmentation, the high abundance of TIMP-2 might also indicate testicular degeneration." (PMID 37888562, 2023).
thrombosis (1 paper, 2021). "For example, it has been shown in mice that MMP‐2 amplifies the response of platelets to weak stimuli, thereby promoting arterial thrombosis and that this process can be abolished by infusion of TIMP‐2." (PMID 33107073, 2021).
Urothelial cell carcinoma (1 paper, 2008). "Urothelial cell carcinoma cell lines were cultured with synthetic and physiological protease inhibitors, including BB94, aprotinin, TIMP1 and TIMP2, and invasion was assessed by the Matrigel assay." (PMID 18665176, 2008).
ventricular fibrillation (1 paper, 2019). A disorder characterized by an electrocardiographic finding of a rapid grossly irregular ventricular rhythm with marked variability in QRS cycle length, morphology, and amplitude. "In a canine ventricular fibrillation (VF) model, the ratios of MMP-2/TIMP-2 were higher, and the Cx43 level was significantly decreased." (PMID 30805212, 2019).
Vertigo (1 paper, 2019). An abnormal sensation of spinning while the body is actually stationary. "MMP-9 and TIMP-1 serum levels were both higher in vertigo patients with VBD, and we further found that upregulation of MMP-9 might be accompanied by the downregulation of TIMP-1 but not by TIMP-2 regulation." (PMID 31474817, 2019).
tumor (336 papers, 1992 to 2026). "While some studies indicate that TIMP2 exerts tumor-suppressive functions, others associate it with enhanced tumor cell survival and proliferation." (PMID 41463322, 2025). "TIMP-2 deficiency favoured the recruitment of cancer myeloid-derived suppressor cells (MDSC) by promoting angiogenesis-associated tumour growth and immunosuppressive cytokines and chemokines." (PMID 38802341, 2024). "TIMP2 treatment compensates for TIMP2 mutation to reveal immunomodulatory and oncogene regulation that inhibits tumor growth and metastatic niche formation." (PMID 38234759, 2023). "These mutant mice lacking exons 2/3 were chosen specifically because this deletion results in the loss of the putative α3β1 integrin-binding domain of TIMP2 shown to mediate its MMP-independent anti-tumor effects, reviewed in." (PMID 38234759, 2023). "Mice harboring a loss-of-function mutation in Timp2 demonstrate a marked increase in tumor growth, and this effect can be rescued with exogenous rTIMP2." (PMID 38234759, 2023). "This suggests that the functional mutation of Timp2 results in enhanced production of myeloid-derived cells in organs of hematopoiesis (spleen) and an increase in their recruitment to tumor sites in wt mice." (PMID 38234759, 2023). "Univariate analysis confirmed that high PD-L1, TWIST1 and TIMP2 were significantly associated with shorter tumor recurrence (p-value < 0.03, < 0.02 and < 0.05, respectively)." (PMID 34885101, 2021). "There are at least 23 MMPs and four types of TIMPs expressed in humans, but MMP-2, MMP-9, MMP-14, TIMP-1, and TIMP-2 are often associated with the tumor invasion process." (PMID 32669083, 2020). "The reduced expression and activity of TIMP2 has been associated with increased invasiveness, advancing tumor stage, poor prognosis, and decreased overall survival in CRC." (PMID 30988064, 2019). "We aim to assess the diagnostic and prognostic usefulness of serum MMP-2 and TIMP-2 as potential biomarkers in comparison to well-established tumor markers of PC (CA 19-9, carbohydrate antigen 19-9 and CEA, carcinoembryonic antigen)." (PMID 30719232, 2019). "Previous reports have highlighted that TIMP2 inhibits tumor-associated angiogenesis and leads to a ‘normalization’ of tumor vasculature." (PMID 31882975, 2019). "Enhanced TIMP-2 expression in the serum and tumor tissues have been associated with a better prognosis in non-small lung cancer (NSCLC) patients." (PMID 29393911, 2018). "A number of studies have reported TIMP-2-mediated inhibition of tumor growth and invasion, while lower levels of TIMP-2 in tumor samples have been associated with tumorigenesis." (PMID 25789040, 2015). "Then, we examined other tumor-associated genes, such as c-myc, E-cadherin, TIMP-2, TIMP-3, and VASH1." (PMID 26452129, 2015). "During cancer progression, high levels of TIMP-2 are associated with the inhibition of tumor growth, angiogenesis, invasion and metastasis, secondary to the inhibition of endothelial cell migration." (PMID 24527080, 2014). "The sequence variants within TIMP2 genes presumably disrupt this balance and are seemingly associated with the susceptibility for the development of tumor growth and progression." (PMID 25136829, 2014). "We used immunofluorescence staining to examine the expression of such an MT1-MMP/TIMP-2 association on the surface of tumor cells during transendothelial migration." (PMID 24194929, 2013). "Upregulated expression of MMP-7 and downregulated expression of TIMP-2 in CCRCC have significant clinicopathological associations with the aggressiveness observed for this tumor." (PMID 23408109, 2013). "In this study, our goals were to investigate the precise role of HSA/TIMP-2 in anti-tumor activity associated with angiogenesis and further define in vivo molecular links between anti-angiogenesis and the modulation of MMP-2." (PMID 22545131, 2012).
tumor (continued). "In this study, we investigated the mechanism underlying the anti-tumor effects of a TIMP-2 fusion protein conjugated with human serum albumin (HSA/TIMP-2)." (PMID 22545131, 2012). "Some genes encode proteins with functions related to signal transduction (PIK3R3, MAPK8IP1, and GATA2), and one gene encodes a protein that regulates tumor invasion and metastasis (TIMP2)." (PMID 17498291, 2007). "Overexpression of TIMP-1 and TIMP-2 is associated with inhibition of apoptosis and invasive tumour growth." (PMID 16207317, 2005). "Both hypoxia and microsphere exposure promoted a pro-angiogenic phenotype, characterized by increased VEGF secretion in radiosensitive tumor and healthy cells, whereas resistant HepG2 cells exhibited angiogenic signaling linked to TIMP2 suppression and IL-8 induction." (PMID 41751824, 2026). "Decreased expression of TIMP2 in MM has been associated with tumor progression and low survival." (PMID 39984959, 2025). "Conversely, reduced expression of TIMP-2 is associated with tumor development and distant metastasis, while overexpression may yield the opposite effect, suggesting that it is not solely related to the inhibition of MMP activity." (PMID 39769318, 2024). "MG from tumor bearing animals show also upregulation of Timp2, Serpine2, Cst7, and Ctsd, genes encoding proteases or their modulators participating in reorganization of extracellular matrix, which may reflect invasion supporting properties." (PMID 33608526, 2021). "Besides, Kaplan-Meier survival analysis revealed that the low expression of TIMP-2 in tumor tissues was associated with poor OS in CRC patients." (PMID 31293204, 2019). "The TIMP2 protein was significantly stronger in the invasive areas than the lepidic areas of Invasive Pulmonary Adenocarcinoma; this has been attributed to increased TIMP2 expression causing elevated ECM accumulation in the invasive tumor cells, resulting in fibrous scar formation." (PMID 31921636, 2019). "Whilst many of these genes may acquire a tumor-associated increase in expression irrelevant of TIMP2, it is likely that a number of these genes result in an alteration of TIMP2 activities within developing tumors that contributes to ECM dysregulation." (PMID 31882975, 2019). "Experimental and clinical data have implicated MT1-MMP and TIMP-2 in tumor progression." (PMID 26331622, 2015). "We also demonstrate that the anti-tumor activity of HSA/TIMP-2 is strongly associated with anti-angiogenesis attributed to a reduction of MMP-2 production but without inhibition of MT1-MMP, indicating that HSA/TIMP-2 plays a more complex role in anti-angiogenesis." (PMID 22545131, 2012). "Thus, high CD3, CD20 or CD68 counts were significantly associated with MMP-9 expression, at the invasive front; whereas high CD68 count was significantly associated with MMP-14 and TIMP2 in this same tumor location." (PMID 23300781, 2012). "Also, we found that high CD68 count and CD68/(CD3+CD20) ratio were associated with both MMP-11 and TIMP-2 expressions by MICs at the tumor center." (PMID 23300781, 2012). "In other clinical analyses, TIMP-2 expression was positively associated with tumor recurrence." (PMID 23320037, 2012). "Based on the mechanistically undefined functions of TIMP2, and reports linking its activity with anti-tumor and anti-aging characteristics, it would be of great interest to assess whether the serum proximal interactomes of targets like TIMP2 could impart clinically relevant diagnostic information." (PMID 38313275, 2024). "However, clinical results of TIMP2 varied with tumor types, which might be caused by different interactions and non-anti-proteolytic functions of TIMPs." (PMID 38408082, 2024). "In addition, we have shown that administration of TIMP2, both directed and systemic, can reduce primary tumor burden, normalize tumor-associated vasculature, reduce infiltration of myeloid-derived suppressor cells and inhibit metastatic niche gene signatures at metastatic target sites." (PMID 31882975, 2019).
tumor (continued). "Reduced levels of TIMP-2 expression may be implicated in tumor progression and spread of disease." (PMID 24527080, 2014). "In contrast, although ICAM-1 and TIMP-2 play relevant roles in tumor progression and extracellular matrix remodeling, the current literature does not provide direct evidence of their transcriptional regulation by miRNA-21." (PMID 41596621, 2026). "The expression of inflammatory and tumor-associated genes (IL-8, MCP-1, TIMP-2, ICAM-1 and NF-kB) was assessed by quantitative PCR." (PMID 42072644, 2026). "Among the targets of Arid4a, MTSS1, RB1, and PTEN are involved in the suppression of tumor cell metastasis, while TIMP2 is believed to be a suppressor of tumor angiogenesis." (PMID 40066676, 2025). "Immunohistochemical analysis confirmed that circLIFR overexpression led to a decrease in Ki-67 expression and an increase in TIMP2 expression within the tumor tissues." (PMID 38914806, 2024). "Besides, the upregulation of HIF-1α in macrophages could increase the expression of miR-193a-5p, and later the exosomes produced by tumor-associated macrophages (TAMs) could traffic the miR-193a-5p towards the 3’ untranslated region (UTR) of TIMP2 mRNA in the RCC cells." (PMID 39296981, 2024). "Among them, the TREM2+ subpopulation was characterized by high expression of GPNMB, TREM2, ACP5, LGMN, and TIMP2, and mainly distributed at the boundary and core region of the tumor." (PMID 38948071, 2024). "Regarding MMPs, a slight decrease was observed in the expression of MMP-9, and the level of TIMP-1 was increased; however, lower levels of MMP-2 and TIMP-2 were detected in tumorous tissues compared to adjacent healthy tissue samples." (PMID 39062015, 2024). "The translation of TIMP2 mRNA would be inhibited, resulting in the increase of vasculogenic mimicry (VM) and tumor progression." (PMID 39296981, 2024). "This study confirmed circLIFR as a novel tumor suppressor delayed PTC progression through the miR-429/TIMP2 axis." (PMID 38914806, 2024). "TIMP-2 contributes to carcinogenesis and the development of MM by promoting tumor cell proliferation and metastasis." (PMID 38708150, 2024). "Dual-expressing (TIMP2 + PADI1) oncolytic adenoviruses had significantly higher anti-tumor activity than single-transgene oncolytic viruses and vehicle control." (PMID 36816748, 2023). "In this study, we present evidence describing the anti-tumor and anti-metastatic capabilities of the matrisome protein TIMP2, using orthogonal approaches." (PMID 38234759, 2023). "Upon uptake by tumor cells, the highly expressed miR-193a-5p promotes tumor angiogenesis, invasion, and proliferation by sponge-adsorbing tissue inhibitor of metalloproteinases 2 (TIMP2)." (PMID 37469514, 2023). "First and foremost, rTIMP2 treatment reduced tumor burden in both wt and mT2 mice, consistent with previous reports that TIMP2 demonstrates significant anti-tumor activity." (PMID 38234759, 2023). "On the other hand, TIMP-2, an MMPs (matrix metalloproteinase) regulator, inhibited cell proliferation, tumour growth, angiogenesis, cancer cell invasion and cancer metastasis." (PMID 35953652, 2023). "Next, we studied the effect of the administration of recombinant human TIMP2–6x-His (rTIMP2) in both mT2 and wt tumor-bearing mice." (PMID 38234759, 2023). "As demonstrated in vitro and in vivo, TIMP-2 treatment to cancer cells prevented cell migration, resulting in reduced tumour growth and less angiogenesis." (PMID 35953652, 2023). "Clinical pathological studies found high levels of cellular signal changes, e.g. HIF1α, HGF and TIMP-2, in the majority of primary tumours and their metastases." (PMID 35953652, 2023). "Treatment with recombinant TIMP2 reduced primary tumor growth in both mutant and wild-type (wt) mice." (PMID 38234759, 2023). "Here we directly demonstrate the tumor suppressor and potential antimetastatic activity of TIMP2 in murine models of NSCLC." (PMID 38234759, 2023).
tumor (continued). "In tumor-bearing wt mice, TIMP2 treatment reduced the expression of upstream oncogenic mediators, whereas treatment of mT2 mice resulted in an immunomodulatory phenotype." (PMID 38234759, 2023). "According to our results, piperine reduced cell migration by regulating MMP2 and MMP9 and their action on their respective antagonists, as TIMP1 and TIMP2 inactivate metalloproteinases and prevent their action, triggering a reduction in tumor cell migration." (PMID 36678600, 2023). "Other KLF4-regulated factors include Ghrelin, TIMP-1 and TIMP-2, ABL, BMI1, Met, GPA33 and Hsp90, which are associated with tumor development and metastasis." (PMID 37031197, 2023). "TIMP2 is one of four TIMPs that regulate the extracellular matrix in the tumor environment by modulating the catalytic activity of a family of zinc-dependent endoproteases called the matrix metalloproteases (MMPs)." (PMID 36816748, 2023). "The loss of exons 2 & 3 in Timp2 causes significant decreases in the expression and protease inhibitory function of TIMP2, which in turn accelerates the tumor progression in mT2 mice." (PMID 38234759, 2023). "TIMP2 displays anti-tumor properties in murine xenograft as well as allograft models of lung adenocarcinoma and triple-negative breast cancer, respectively." (PMID 38234759, 2023). "We also investigated the effect of daily, systemic recombinant human TIMP2 (rTIMP2) delivery in tumor-bearing mice in a series of studies that highlight TIMP2 as a tumor-suppressor that functions within the tumor microenvironment of the diseased lung." (PMID 38234759, 2023). "Mounting evidence suggests that the tissue inhibitor of metalloproteinases-2 (TIMP2) can reduce tumor burden and metastasis." (PMID 38234759, 2023). "TIMP2 protein, however, despite being thought of mainly as a tumour suppressor, has displayed promoting properties in vitro and has been linked with poorer patient survival (reviewed in 40)." (PMID 37760543, 2023). "LPS suppressed tumour growth in any conditions whilst increased TIMP-2 and anti-cancer neutrophil marker expressions and decreased macrophage marker expressions compared to those in the LPS-untreated groups." (PMID 35953652, 2023). "On the other hand, the results of clinical sample analysis showed an inverse correlation between miR-106a and TIMP-2 expression since re-expression of TIMP-2 led to the restriction of tumor cell migration, invasion, and MMP expression in CC cells." (PMID 37627777, 2023). "Loss-of-function mutation of Timp2 and TIMP2 treatment in mouse NSCLC models reveal tumor suppression via immunologic and oncogenic pathways." (PMID 38234759, 2023). "Despite few reports to the contrary, growing evidence suggests that TIMP2 principally displays anti-tumor capabilities in a manner that is not limited to its role in MP inhibition." (PMID 38234759, 2023). "While there are various in vitro studies and clinical prognosis reports linking TIMP2 with tumor cell survival and proliferation." (PMID 36624735, 2022). "After transfecting Caki-1 and 786-O cells with TIMP2-cDNA (oeTIMP2) versus pWPI-cDNA, the tumor cells were collected for 2D/3D VM assays and invasion assays after coculture with/without TAMs." (PMID 35443741, 2022). "In the non-invasive tumor group there was only one significant correlation, between TIMP-2 and MMP-2 expression (rho = 0.378, p = 0.039)." (PMID 36551933, 2022). "A recent study also revealed inhibitory effects of TIMP-2 on tumor growth and metastasis in murine model of TNBC." (PMID 36741729, 2022). "Immunohistochemical (IHC) analysis showed that tumor tissues, which showed elevated TIMP-2 expression levels exhibited resistance to 5-Fu." (PMID 35022331, 2022). "TIMP-2 adenoviral delivery inhibited tumor growth, angiogenesis and metastasis in MDA-MB-231 breast tumor xenografts." (PMID 36741729, 2022).